BCL2 (BCL2 apoptosis regulator)
Diseases named in the same sentence as BCL2 in open-access papers (continued):
Sharing a sentence is not in itself a finding about the gene and the disease.
melanoma (continued). "Additionally, due to gamma-secretase and B-cell lymphoma 2 (Bcl-2) expression of melanoma CSCs, correlated with that of ALDH, the administration of their inhibitors, i.e., gamma-secretase inhibitors (GSI) and myeloid cell leukaemia sequence 1 (MCL-1)—an inhibitor of Bcl-2—is targeting CSCs." (PMID 35334544, 2022). "MiR-204-5p by targeting MMP9 and Bcl-2 could inhibit melanoma growth and resistance to 5-FU." (PMID 33954114, 2021). "Additionally, a previous study has demonstrated that Bcl-2 overexpressing melanoma cells, under low oxygen conditions, induce the HIF-1α cascades through modulation of nuclear factor κB (NF-κB) and other transcription factors to induce transcriptional activation of VEGF." (PMID 32859045, 2020). "The aim of this study was to evaluate whether bcl-2 expression in melanoma cells could influence tumor-promoting functions of tumor-associated macrophages, a major constituent of the tumor microenvironment that affects anticancer immunity favoring tumor progression." (PMID 32269145, 2020). "As both melanoma cells and macrophages exposed to supernatants from bcl-2-overexpressing cells expressed higher levels of the receptors for IL-1β, IL-17, IL-8 and CCL2, it is conceivable that these cytokines may critically support an active interplay between the tumoral and stromal compartments." (PMID 32269145, 2020). "It was shown to be downregulated and might function as a tumor suppressor by targeting Myc, FSCN1 in gastric cancer, ZEB1 in oral squamous cell carcinoma, CRKL in hepatocellular carcinoma, TLN1 in nasopharyngeal carcinoma, AKT1 in melanoma, or BCL2 and SP1 in esophageal carcinomas." (PMID 33414893, 2020). "Our data indicated higher B-cell CLL/lymphoma 2 (BCL2) expression in melanoma without BRAF hotspot mutations, suggesting that BH3 mimetics, such as ABT-199 (venetoclax, a small molecule against BCL2), may be a potential therapeutic option for these patients." (PMID 32764384, 2020). "Moreover, treatment with a specific inhibitor of Bcl-2 induced downregulation of miR-378a-5p in melanoma cells, thus indicating that pharmacologic inhibition of Bcl-2 could exert its effect also through modulation of miR-378a-5p functions." (PMID 32060259, 2020). "Due to the synergy we observe with this combination in vitro in several melanoma cell lines, (and the apparent high BCL-2 expression in melanoma patient tissue), this could provide the most attractive avenue for future investigation of BH3-mimetics in melanoma." (PMID 31019203, 2019). "This suggests that miR‐15b may promote apoptosis independently of Bcl‐2 in melanoma cells." (PMID 30499222, 2019). "Furthermore, downregulation of antiapoptotic Bcl-2 proteins (Bcl-2, Mcl-1, and Bcl-xL) was reported in melanoma cells upon treatment with different therapeutic strategies used for TRAIL sensitization, such as chemotherapeutics and inhibitors for metabolism, HDACs, and kinases." (PMID 31083589, 2019). "By using M14 and A375SM-SC1 melanoma cell lines and their derivatives stably overexpressing wild-type Bcl-2, we evaluated whether Bcl-2, a protein involved in melanoma progression, resistance to apoptosis, and poor prognosis, plays a role in the regulation of Sema5A expression." (PMID 30454024, 2018). "Our results emphasize this anti-cancer role of piceatannol by exhibiting that the capability of piceatannol to restrain melanoma cells growth by partially influencing Bax, Bcl-2 and caspase-3 expression in apoptosis, suggesting that piceatannol could be used for the treatment of melanoma." (PMID 29041990, 2017). "A major obstacle in the treatment of malignant melanoma is its resistance to classical chemotherapy and radiotherapy, which may be due, in part, to a natural resistance to apoptosis attributed to high levels of anti-apoptotic Bcl2 proteins." (PMID 27384486, 2016).
melanoma (continued). "What is certain is that we are at the beginning of understanding how BCL-2 proteins promote melanoma survival and apoptosis, and how these proteins may be pharmacologically targeted to increase primary treatment responses and perhaps treat drug resistant disease." (PMID 26501069, 2015). "Preclinical data in melanoma mouse xenografts and osteosarcoma cells, showed that dinaciclib induces apoptosis, increases Bax and Bim in mitochondria, and decease antiapoptotic factors, such as Mcl-1, Bcl-2, Bcl-xL and XIAP, as well as phosphorylation of Ser2 of RNA Pol II." (PMID 25596730, 2015). "Furthermore, melanoma tumors treated with DM-1 showed a decreased Bcl-2/Bax ratio." (PMID 25742310, 2015). "Therefore we asked whether down-regulation of CD271 in melanoma cells may affect levels of anti-apoptotic genes like cIAP-1, cIAP-2 and BCL-2." (PMID 24799129, 2014). "In melanomas, the anti-apoptotic proteins Bcl-2, Bcl-xL, and Mcl-1 appear to increase while the pro-apoptotic protein Bax decreases with the progression of primary melanoma tumors and melanoma cells and might be involved in resistance to conventional therapies." (PMID 24647338, 2014). "Similarly, high expression was observed in the A375-WT group, suggesting that G6PD may regulate cell apoptosis of melanoma through apoptosis-related factors Fas, Bcl-2, and Bcl-xL." (PMID 23693134, 2013). "Taken together, these data suggest that the pro-apoptotic synergy between Maritoclax and ABT-737 is, at least in part, due to the degradation of Mcl-1 induced by Maritoclax and simultaneous inhibition of Mcl-1 and Bcl-2 may be an effective strategy for melanoma therapy." (PMID 24223823, 2013). "In addition, primary human fibroblasts from skin were studied in order to identify those antiapoptotic Bcl-2 proteins whose loss specifically affects melanoma cells while sparing non-malignant cells." (PMID 22292048, 2012). "Therefore, simultaneous inhibition of MITF and BCL2 may be especially potent by sensitizing melanoma cells to apoptosis." (PMID 22927992, 2012). "In summary, dysregulation of Bcl-2 proteins appears of critical importance for melanoma cell survival and drug resistance, and among the fast increasing number of new targeted therapies, those, which affect Bcl-2 proteins, may especially apply for melanoma." (PMID 19506730, 2008). "High expression of Bcl-2 antiapoptotic proteins, such as Bcl-2, Bcl-XL, and Mcl-1, may also contribute to melanoma progression and chemoresistance as antisense oligos against these genes can induce death of melanoma cells." (PMID 15305193, 2004). "GAS5 promotes apoptosis in melanoma; GAS5 knockdown induces G1/S progression and inhibits apoptosis by upregulating Bcl‐2, whereas GAS5 overexpression decreases Bcl‐2." (PMID 41463281, 2025). "Functionally, knocking down GAS5 in melanoma cells accelerates G1/S progression through increases in cyclin D1, CDK4, and p27; boosts viability; and blunts apoptosis via increased expression of Bcl-2." (PMID 41463281, 2025). "Western blot analysis revealed GEF-induced caspase-9 and -3 activation, PARP cleavage, and Bcl-2 downregulation, suggesting induction of apoptosis by GEF in melanoma cells." (PMID 39941974, 2025). "Here, we report that GCNT2/I-branching significantly impairs Gal-3 binding to melanoma cell receptors, particularly β1 integrin, and diminishes Gal-3-induced ERK phosphorylation, BCL2 expression, cell proliferation, and migration." (PMID 40430022, 2025). "For example, Bcl-2 is more highly expressed in melanocytes than in many other cell types, and its relative BCL2A1 is amplified in 30–40% of melanomas." (PMID 40721981, 2025).
melanoma (continued). "RI treatment led to the downregulation of CCND1, MYC, and BCL2 in proliferative cell lines, further supporting the role of NSD2 in melanoma progression." (PMID 40386826, 2025). "Co-inhibition of MCL1 with BCL2 or BCLXL induces apoptosis in both bulk melanoma cells and therapy-resistant melanoma-initiating cells." (PMID 41155156, 2025). "In contrast to monotherapy with BH3-mimetics, the combination of Mcl-1 inhibitors with Bcl-2 inhibitors showed promising activities against BRAFV600E-mutant and BRAF-wildtype melanomas." (PMID 39935431, 2025). "Previously published studies also described the upregulation of BAX and the downregulation of BCL-2 expression levels in G361 and SK-MEL-2 melanoma cells treated with 0.5 μM binimetinib." (PMID 41373567, 2025). "This downregulation of ERK led to reduced PKM2 activation, decreased expression of the anti-apoptotic protein Bcl-2, and increased expression of the pro-apoptotic protein BAX, collectively promoting apoptosis in melanoma cells." (PMID 41463545, 2025). "In another study, the co‐treatment of eugenol and cisplatin reduced cell proliferation and induced apoptosis in G361 melanoma cells via inhibited MMP and proteasome activity, increased Bax and caspase‐9/7/3 expression, and declined Bcl‐2 expression." (PMID 40761498, 2025). "In both melanoma cell lines, RSV treatment elevated the Bax/Bcl-2 ratio, promoting mitochondrial outer membrane permeabilization and facilitating cytochrome c release." (PMID 41614770, 2025). "Flavokawain B, a chalcone, induces ROS-mediated autophagy in melanoma A375 cells by inhibiting mTOR, increasing LC3-II levels, and dysregulating Beclin 1/Bcl-2 levels." (PMID 39371094, 2024). "MC extract administration induced the amelioration of melanoma by controlling the PAX3/PTEM/PIP3/Akt/mTORC1 and PAX3/MITF/CDK2·c-Met·Bcl2·RAB27A signaling pathways, which are involved in melanoma proliferation and invasion." (PMID 39684511, 2024). "The MC extract also decreased the expression of MITF, CDK2, c-Met, Bcl2, and RAB27A, which had increased with melanoma cell treatment." (PMID 39684511, 2024). "In the current study, melanoma cell treatment increased the expression of MITF and its downstream genes CDK2, c-Met, Bcl2, and RAB27A." (PMID 39684511, 2024). "ADA inhibits the PI3K/Akt pathway and its downstream target NF-κB in melanoma cells, reduces the expression of the anti-apoptotic proteins c-FLIP, XIAP and Bcl-2, and promotes the activation of caspase-3 and PARP to induce apoptosis." (PMID 38448410, 2024). "ADT-OH inhibits the activation of NF-κB in B16F10 melanoma cells, reduces the expression of downstream target genes of NF-κB pathway (e.g. XIAP, Bcl-2), and induces cell apoptosis via mitochondrial pathway." (PMID 38448410, 2024). "BCL2 proteins are those crucial modulators which enclose some pro- and anti-apoptotic factors like BCL2 and BAX and participate in the survival and apoptosis of melanoma." (PMID 39726752, 2024). "In melanoma cells, MiR-1246 inhibited BAX but stimulated Bcl2, thus inhibiting apoptosis and hepatocyte nuclear factor 3-β/FOXA2 which is involved in embryonic development and activates liver genes." (PMID 38899393, 2024). "Quantitative real-time PCR was used to determine gene expression variations of anti-apoptotic Bcl-2 and pro-apoptotic BAX to further establish the pro-apoptotic effects of the three triterpene-gold nanoformulations on A375 melanoma cells." (PMID 36615613, 2023). "RT-qPCR analysis showed a fold change increase in the expression of BAX and a decrease in the expression of Bcl-2, which occurred in the triterpene-GNP conjugate-treated A375 melanoma cells." (PMID 36615613, 2023). "For example, combining copper chelation with tetrathiomolybdate (TTM) and the Bcl-2 inhibitor ABT-263 reduces cell viability and induces apoptosis in BRAFV600E-driven melanoma cells." (PMID 38186578, 2023).
melanoma (continued). "We investigated the effect of three generations of mTOR kinase inhibitors alone and in combination with the MEK1/2 kinase inhibitor AS-703026 on the expression of pro-survival proteins: p-Bcl-2 (T56), Bcl-2, Bcl-xL, and Mcl-1 in MEWO melanoma cell line." (PMID 37097377, 2023). "Five shikonin derivatives containing deoxyshikonin exhibit in vitro and in vivo anticancer effects by inducing murine melanoma B16F10 cells apoptosis and arrest in the sub‐G1 phase through repression of Bcl‐2 proteins and activation of Bax expression." (PMID 37155410, 2023). "Treatment of melanoma cells reduced STAT3 phosphorylation (Y705), inducing apoptosis via activation of Bax, reduction in Bcl-2 expression, and caspase-3 cleavage." (PMID 37181747, 2023). "It was proposed that upregulation of these MAPK kinases promotes apoptosis in melanoma cells, which was supported by the expression of BAX, BCL-2, and cleaved PARP." (PMID 36829966, 2023). "In conclusion, our study demonstrated that LMW-F inhibits the proliferation of melanoma cells by targeting the PTEN/AKT signaling pathway and Bcl-2 phosphorylation." (PMID 38186578, 2023). "LNPs loaded with microRNAs effectively inhibited their target oncogenes, Bcl-2 and VEGF-A, impaired melanoma cell proliferation and viability, and potentiated the efficacy of MAPKi." (PMID 37622997, 2023). "In our recent work, we showed that bezotriazole esters of BA, OA and UA, respectively, did reduce the expression of the anti-apoptotic Bcl-2 gene and induced an increase in the fold gene expression of the pro-apoptotic BAX in A375 melanoma cells." (PMID 36615613, 2023). "Follow mitochondrial translocation, Nur77 binds to Bcl-2 and converts Bcl-2 from a survival to a killer of cancer cells, thereby inhibiting the growth and induce apoptosis of MV3 melanoma cells." (PMID 36686679, 2022). "BNIP3 is a protein that interacts with the antiapoptotic protein Bcl-2, and it is showed that BNIP3 drives the migration and invasion of melanoma cells and promotes angiogenesis by regulating integrin-related proteins." (PMID 35783530, 2022). "Bcl-2 and Bcl-XL proteins were also found to cooperate with hypoxia to induce MMP-2 expression in melanoma." (PMID 36224457, 2022). "Overexpression of KYNU can promote changes in apoptotic BCL-2, metabolic KYN, 3-HAA, invasion and migration MMP9, E-cadherin, and other related proteins in melanoma." (PMID 35893303, 2022). "To this regard, we observed that melanoma as well as NSCLC cells, having relative higher levels of endogenous Bcl-2 and Mcl-1 proteins, respect to breast and colon cancer cells, were more sensitive to treatment." (PMID 35265218, 2022). "Based on qPCR and western blotting analysis, we found that the mRNA and protein levels of the apoptosis-related factor Bcl2 were significantly increased in A875 and SK-MEL-110 melanoma cells overexpressing PRPS1." (PMID 36203561, 2022). "The same trend was observed in melanoma cells treated with EPI, which significantly increased the mRNA expression of BAX and decreased the mRNA expression of BCL2, BIRC5, and MCL-1." (PMID 35877720, 2022). "To clarify the roles of AKT and BCL-2, we used AKT siRNA or navitoclax, respectively, the latter of which is a pro-apoptotic BH3-mimetic used in clinical trials for melanoma and other cancers, along with BRAF/MEK inhibition." (PMID 35216449, 2022). "It is a positive regulator of the anti-apoptotic gene BCL2 (BCL2 apoptosis regulator) both in normal melanocytes and in human cutaneous melanoma cells, and of BIRC7 (baculoviral IAP repeat containing 7) in melanoma cells." (PMID 35682684, 2022).
melanoma (continued). "The average level of KIT in melanoma was 65-fold higher than that in adjacent normal tissues, whereas PTEN, cAMP, and BCL2 were downregulated almost twofold." (PMID 35893303, 2022). "The proteins related to the survival of melanoma cells mainly include Galectin-3, Survivin, Dickkopf (DKK), Bcl-2, and so on." (PMID 36338621, 2022). "The anti-apoptotic BCL-2 proteins, including MCL-1 and BCL-XL, play a critical role in the survival of these hard-to-treat melanoma cells." (PMID 34575429, 2021). "Other oncogenes that are epigenetically regulated and important for melanoma tumorigenesis include MDM2 and BCL-2." (PMID 34944799, 2021). "Phosphorylated STAT5 is regulated by rEGF in melanoma, and inhibition of STAT5B expression can significantly reduce the expression of BCL-2, resulting in decreased cell survival rate and increased apoptosis." (PMID 33732282, 2021). "One of the first small molecules used in melanoma was the pan BH3 inhibitor obatoclax (GX15-070), showing affinity for Bcl-2, Bcl-xL, Mcl-1, Bcl-w and A1/Bfl-1." (PMID 33803452, 2021). "The expression of apoptotic genes including BAX, BCL2, and CASP3 was evaluated in B16-F10 melanoma cancer and L929 cells by real-time PCR assay." (PMID 34825002, 2021). "In order to evaluate the potential of the apoptosis induction of complex 1, melanoma B16F10 and sarcoma 180 were treated with the complex and the genes from the apoptotic pathway BCL-2 and Caspase 3 had their expression analyzed with real-time PCR." (PMID 34961767, 2021). "In a transgenic mouse model with overexpression of IL4, IL4/IL4Rα suppressed the development of melanoma through activation of the P21-mediated STAT6 pathway and inhibition of anti-apoptotic BCL2 expression." (PMID 33419470, 2021). "Of the proteins that were measured across all three tumor datasets, we observed that CD4, CD45RO, GZMB, Ki67, PTEN, Bcl-2, CD19/20, and Pan-CK are positively correlated with CD8 in GBM and in at least one melanoma treatment arm." (PMID 34188042, 2021). "In sarcoma 180, the gene of caspase 3 was also upregulated at the 1.5 μM treatment, but differently from the observed in melanoma B16F10, the expression of BCL-2 was upregulated." (PMID 34961767, 2021). "It was also found that silencing UBTF downregulated Bcl-2 protein expression and upregulated Bax protein expression in melanoma cell, whereas UBTF overexpression increased Bcl-2 expression and decreased Bax expression." (PMID 34663332, 2021). "A similar observation of HuR silencing, resulting in BCL-2 reduction, was observed in SK-MEL-3 and WM39 melanoma cell lines." (PMID 33418925, 2021). "Upregulation of miR-182 promotes migration and survival in human melanoma cell lines by preventing the transcription factors, MITF-M and FOXO3, and downregulates Bcl-2, cyclin D2, c-Met, the Akt and ERK1/2 pathways while increasing β-catenin expression." (PMID 34067095, 2021). "HuR-NP treatment significantly diminished protein expression of HuR, Cyclin D1, Cyclin E1, BCL-2, HIF1-α, VEGEF-A, and an increased expression of p27 at both 24 h and 48 h in melanoma cell lines (p < 0.05)." (PMID 33418925, 2021). "At the transcriptional level, MITF controls genes involved in cell survival (BCL2, HIF1A, BCL2A1), migration (DIAPH1, MET) and proliferation (CDK2, TBX2, CDKN1B), providing important signals for growth of melanoma cells." (PMID 34289891, 2021). "The compounds induced caspase-dependent apoptosis in melanoma cells through upregulation of the Fas and DR5 death receptors and regulation of Bcl-2 family members (Bcl-2, Bcl-xL, and Bax)." (PMID 32340351, 2020). "BCL-2 was weakly expressed in all MPM cell lines and all other lines examined except DMS53 (small-cell lung cancer) and CHL-1 (melanoma)." (PMID 33298868, 2020).